CTLA4 (cytotoxic T-lymphocyte associated protein 4)
Diseases named in the same sentence as CTLA4 in open-access papers (continued):
Sharing a sentence is not in itself a finding about the gene and the disease.
melanoma (continued). "An increase in CTLA4 and PD-1 expression was seen in the low-risk group, and anti-PD-1/PD-L1 antibodies were less effective against pancreatic cancer than they were against melanoma, renal cell carcinoma, and non-small cell lung cancer, owing to immunostasis or drug resistance." (PMID 36359832, 2022). "The RAS/RAF/MEK/ERK signalling pathways determine the resistance of melanoma cells to inhibitors used in immunotherapy, which is based on the blocking the checkpoints programmed death-1 (PD-1) or cytotoxic T-lymphocyte-associated protein 4 (CTLA4) by antibodies." (PMID 36613640, 2022). "In the clinic, melanoma patients who were treated with immune checkpoints inhibitors targeting PD-1 (Programmed cell Death protein 1), PD-L1 (Programmed cell Death protein ligand 1) and CTLA-4 (Cytotoxic T-Lymphocyte-associated antigen 4) can become resistant and harbored an upregulated EZH2." (PMID 36230787, 2022). "While the loss of INF-γ signaling was shown to induce resistance to anti-CTLA-4 treatment, the introduction of beneficial bacteria was shown to be associated with significantly higher levels of this cytokine in the tumor-draining lymph nodes of melanoma mice models." (PMID 34360802, 2021). "In mouse models of melanoma, NK or CD8+ T cell depletion caused significant reduction in the survival of melanoma when treated with anti-PD-1 + anti-CTLA-4, supporting the hypothesis that NK and CD8+ T cells cooperate with each other to eradicate the tumor in response to these therapies." (PMID 33802954, 2021). "Moreover, baseline gut microbiota enriched with Faecalibacterium and other Firmicutes was associated with beneficial clinical response to immune checkpoint inhibitor targeting cytotoxic T-lymphocyte-associated protein 4 (CTLA-4) (Ipilimumab) in melanoma patients." (PMID 34360566, 2021). "Moreover, several groups have substantiated the role of neoantigens in response to ICIs, supported by evidence of higher neoantigen load being associated with better therapeutic response to CTLA-4 and PD-1 blockade in patients with melanoma and non-small-lung cancer." (PMID 33207653, 2020). "Therefore, our study confirmed for the first time that TERT mutation could be used as a predictive marker for anti‐CTLA4 treatment, especially for melanoma." (PMID 32810393, 2020). "Furthermore, in melanoma patients, high levels of circulating neutrophils and neutrophil-to-lymphocyte ratio have been associated with resistance to anti-CTLA-4, indicating the main role that these cells may exert in inhibiting immune response." (PMID 32423420, 2020). "Two autoimmune germline variants as potential biomarkers of anti-CTLA4 or anti-PD1 immune checkpoint inhibitors (ICI) efficacy in melanoma were identified and suggests that underlying genetic susceptibility to autoimmunity may play an important role during ICI treatments." (PMID 32894202, 2020). "The recent success of immunotherapy in melanoma relates to the use of monoclonal antibodies directed against the immune checkpoints such as programmed cell death protein-1 (anti-PD-1; pembrolizumab, nivolumab) and cytotoxic T-lymphocyte-associated protein-4 (anti-CTLA-4; ipilimumab)." (PMID 31974367, 2020). "However, the results showed that only patients with melanoma with TERT mutation could more likely benefit from anti‐CTLA4 treatment." (PMID 32810393, 2020). "Furthermore, patients with CTLA-4 gene variant 1661A>G may predispose melanoma patients to the development of endocrine irAEs." (PMID 31293970, 2019). "On the other hand, melanoma is an immunogenic cancer, conferring sensitivity to immunotherapeutic antibodies, which augment the cell-mediated immunity, such as checkpoint inhibitors against cytotoxic T-lymphocyte-associated antigen 4 (CTLA-4) or programmed cell-death protein 1 (PD-1)." (PMID 31164959, 2019).
melanoma (continued). "Thus, investigation has focused on therapies directed at immune targets, resulting in the main approved therapeutic agent for melanoma used nowadays, ipilimumab (human monoclonal antibody (IgG1k) against the cytotoxic T-lymphocyte-associated antigen-4 (CTLA-4))." (PMID 31167479, 2019). "In contrast to anti-CTLA-4 monotherapy, the use of anti-PD-1 pembrolizumab monotherapy (10 mg/kg every 2 weeks for up to 2 years, followed by 2 mg/kg every 3 weeks) for asymptomatic melanoma BMs (n = 23) was associated with a 2-year OS rate of 48% and median OS of 17.0 months (NCT02085070)." (PMID 30854898, 2019). "Therapeutic antibodies targeting cytotoxic T-lymphocyte-associated protein 4 (CTLA-4) or the axis of programmed cell death protein 1 (PD-1) and its corresponding ligand PD-L1 have shown compelling results in several different cancer types, including metastasized melanoma and lung cancer." (PMID 31395068, 2019). "In addition to the nonspecific immunotherapies, three immune checkpoint modulators, ipilimumab (anti-cytotoxic T-lymphocyte associated antigen 4 [CTLA-4]), nivolumab (anti–programmed cell death protein 1 [PD-1]), and pembrolizumab (anti–PD-1), have been approved for the treatment of melanoma." (PMID 30956763, 2019). "However, in 2011, the advanced melanoma treatment landscape was revolutionised with the approval of the anti-cytotoxic T-lymphocyte-associated protein-4 checkpoint inhibitor ipilimumab and the selective BRAF kinase inhibitor vemurafenib, both of which significantly improved overall survival." (PMID 30031393, 2018). "With approval of ipilimumab with nivolumab for front-line treatment in melanoma and renal cell carcinoma and likely approval for high mutational load non-small cell lung cancer, we believe that optimization of management for anti-CTLA-4 induced colitis will continue to be relevant." (PMID 30305177, 2018). "In patients with melanoma, whole exomes from pre-treatment melanoma tumour biopsies and matching germline tissue samples were examined to determine if neoantigen burden affects responses to antibodies directed against cytotoxic T lymphocyte-associated antigen-4 (CTLA4)." (PMID 28716075, 2017). "Because NY-ESO-1 is expressed in a number of solid tumors and 30–40% of advanced melanoma patients, it has been examined as a specific biomarker for increased T and B cell reactivity after CTLA-4 blockade, and if such reactivities could be associated with positive clinical outcome." (PMID 24904570, 2014). "Metastatic melanoma prognosis remains poor and clinical success is still limited at this stage of the illness even if new treatments appear promising such as therapies targeting the CTLA-4 (cytotoxic T-lymphocyte associated antigen-4) or the mutated form of BRAF." (PMID 23284620, 2012). "A similar pattern was detected in melanoma patients receiving combined anti‐PD‐1 and anti‐CTLA4 treatment." (PMID 41527493, 2026). "On the other hand, immune checkpoint inhibitors including PD‐1/PD‐L1 inhibitors and cytotoxic T‐lymphocyte antigen 4 (CTLA‐4) inhibitors changed the treatment landscape of advanced melanoma." (PMID 41492362, 2026). "The relevance of response to anti-PD-1 and anti-CTLA-4 therapies among subtypes was predicted using melanoma datasets." (PMID 41596347, 2026). "In conclusion, a PD-1 inhibitor combined with a CTLA-4 inhibitor is a very effective method for the treatment of melanoma, but the incidence of various types of adverse reactions is high, and the evidence is not reliable." (PMID 42123452, 2026). "Accordingly, among the genes investigated, CXCL8 and CTLA4 were identified as significantly upmodulated genes in melanoma cultures." (PMID 41596411, 2026). "We used medical subject words and free text words (such as "PD-1 inhibitor", "CTLA-4 inhibitor", "melanoma") as search keywords to search the literature in six literature databases from the establishment of the database to 11 April 2025." (PMID 42123452, 2026).
melanoma (continued). "Although most work has focused on adaptive checkpoints (PD-1 and CTLA-4), accumulating evidence implicates innate immune suppression and stem-like, drug-resistant melanoma cell states." (PMID 42126185, 2026). "Similar results were observed in DFCI samples of melanoma patients receiving anti-CTLA-4 therapy and UCLA samples of patients receiving anti-PD-1 therapy." (PMID 41535256, 2026). "Immunotherapy, such as programmed cell death 1 (PD‐1)/programmed cell death ligand 1 (PD‐L1)/cytotoxic T‐lymphocyte antigen 4 (CTLA‐4) inhibitors, is another parallel approach for the treatment of melanoma." (PMID 41492362, 2026). "In patients treated with an anti–CTLA-4 therapy, the biomarker score remained predictive of OS across clinical subgroups, including male, female, and melanoma (HRs <1), suggesting that its prognostic value is likely robust in these cohorts." (PMID 41295982, 2026). "In conclusion, in heavily pretreated melanoma, nivolumab/ipilimumab induces durable responses in a minority of patients, with reduced efficacy after prior anti-CTLA-4 exposure." (PMID 42050807, 2026). "In melanoma, we identified an 8-gene signature (CD28, CD80, CD86, CTLA4, FAS, IFNG, IL10, and IL12A) associated with survival." (PMID 42216340, 2026). "In melanoma datasets, a CS2-like transcriptomic pattern was associated with improved response to anti-PD-1 therapy, with the combination of anti-PD-1 and anti-CTLA-4 showing more favorable response patterns compared to anti-PD-1 monotherapy." (PMID 41596347, 2026). "The present study aimed to investigate the function of CTLA-4 in cancer cells by investigating the consequences of CTLA-4 depletion in melanoma cells." (PMID 41639053, 2026). "Immunotherapies, including immune checkpoint inhibitors like anti-CTLA-4 and anti-PD-1/PD-L1, have revolutionized treatment, improving survival outcomes for advanced-stage melanoma patients." (PMID 41595691, 2026). "In melanoma, CTLA-4 and vascular endothelial growth factor A blockade elicited a humoral response to Galectin-3 that correlated with improved patient outcomes." (PMID 41477833, 2026). "The objective is to assess the effectiveness and safety of combining PD-1 inhibitors with CTLA-4 inhibitors for melanoma treatment, drawing on current meta-analysis findings and evaluating the supporting evidence." (PMID 42123452, 2026). "Adding the PI3K eganelisib broke the tolerance of the tumor model of 4T1 (breast) and B16 (melanoma) to combination anti-PD-1 and anti-CTLA4 resulting in complete remission of tumors in 30% and 80% of the animals, respectively." (PMID 41256311, 2025). "In melanoma and bladder cancer models, combining EZH2 inhibitors with anti-cytotoxic T-lymphocyte-associated antigen 4 (CTLA-4) therapy demonstrated a direct role for EZH2-mediated T-cell reprogramming in enhancing anti-tumor immunity." (PMID 40040700, 2025). "In melanoma, the combination of ipilimumab (CTLA-4 inhibitor) and nivolumab (PD-1 inhibitor) has shown significant improvements in survival rates compared to monotherapy." (PMID 40170852, 2025). "Combined anti-CTLA-4 and anti-PD-1 treatment is highly effective against melanoma and is being tested in several clinical trials for various cancers." (PMID 40605058, 2025). "Recent studies have demonstrated that the hypolipidemic drug bezafibrate, when combined with CTLA-4 monoclonal antibody therapy, synergistically inhibits melanoma growth." (PMID 40866941, 2025). "Currently three different types of immune checkpoint inhibitors (ICIs) are approved for the treatment of advanced melanoma: CTLA-4 inhibitor (ipilimumab), PD-1 inhibitor (pembrolizumab and nivolumab) and LAG-3 inhibitor (relatlimab)." (PMID 40507314, 2025). "In particular, combining IDO1 inhibitors with PD-1 or CTLA-4 blockade has demonstrated enhanced anti-tumor effects in early phase clinical trials, particularly in melanoma and advanced GBM models." (PMID 41233805, 2025).
melanoma (continued). "Agents targeting immune checkpoint inhibitors (ICIs), including CTLA-4, PD-1, and PD-L1, have significantly improved survival and are now the standard of care for advanced melanoma." (PMID 40936894, 2025). "Our study reports that melanoma and combinatorial blockade of CTLA-4 and PD-1 evoke neuroinflammatory responses (microglial activation), potentially orchestrating neurodegenerative consequences, including synaptic and myelin loss." (PMID 40313772, 2025). "Ipilimumab, a fully human IgG1 monoclonal antibody against cytotoxic T-lymphocyte-associated protein 4 (CTLA-4), is an effective treatment for melanoma." (PMID 39859113, 2025). "The melanomas with brain metastases (BM) showed higher expression of CTLA-4, and lower expression of 4-1BB, CD163, GITR, IDO1, PR, EPCAM and ER-alpha than the melanomas without metastases." (PMID 40621453, 2025). "Although anti-PD-1 or anti-CTLA-4 monotherapy was effective in advanced melanoma, long-term outcomes were limited." (PMID 40647561, 2025). "Third, we divided patients with melanoma (PRJEB23709) following anti-PD-1 + CTLA-4 therapy into high and low FerrScore groups." (PMID 40463869, 2025). "Typical ICIs include monoclonal antibodies against PD-1, PD-L1, and CTLA-4, which have been approved for clinical use in treating various solid tumors such as melanoma, NSCLC, RCC, and TNBC." (PMID 40385461, 2025). "In this paper we use multimodal spatial profiling and conventional histology to study six metastatic melanomas that exhibited persistent residual (stable) radiographic disease following anti-CTLA4 and/or anti-PD1 directed immunotherapy." (PMID 41473281, 2025). "For example, in patients with melanoma, combination therapy with all-trans retinoic acid and CTLA-4 blockers has been shown to reduce circulating MDSC numbers." (PMID 40352926, 2025). "Despite these data, the use of immunotherapy in a patient with BRAF wild-type melanoma and, more specifically, the use of combined CTLA-4 and PD-1 checkpoint-inhibition therapy with recurrent resectable melanoma is a rational therapeutic choice." (PMID 39940799, 2025). "More specifically, increased BMI is associated with increased PFS and overall survival (OS) in male melanoma patients receiving the anti-CTLA4 agent ipilimumab plus the chemotherapeutic agent dacarbazine or PD1-PDL1 axis inhibition." (PMID 40565936, 2025). "Approximately 55% of melanoma patients exhibit intrinsic resistance to monotherapy with PD-1 inhibitors, and around 40% show intrinsic resistance to the combination of CTLA-4 and PD-1 inhibitors." (PMID 41346595, 2025). "Available data from early trials of CTLA-4 monotherapy, such as ipilimumab in melanoma, suggest a relatively low incidence of pneumonitis (typically <1%)." (PMID 40842533, 2025). "Similar outcomes were documented when the delivery of B. fragilis into mice by fecal microbial transplantation enhanced the efficacy of anti-CTLA-4 immunotherapy for melanoma." (PMID 40927726, 2025). "Across 20 studies, strong evidence supports using ICIs, particularly PD-1/PD-L1 and CTLA-4 blockers, as frontline or salvage therapy for melanoma." (PMID 41527622, 2025). "In contrast, the application of CTLA-4 inhibitors is mainly focused on specific cancer types such as melanoma." (PMID 41552828, 2025). "In parallel, we have also utilized melanoma and squamous lung carcinoma cell lines that naturally express CTLA4." (PMID 39404738, 2025). "While both CTLA-4 and PD-1 blockade were first shown to be effective in advanced melanoma, subsequent clinical experience has demonstrated that PD-1/PD-L1 inhibition is generally safer and more effective than CTLA-4 blockade when used as monotherapy." (PMID 41463268, 2025). "One study indicated that melanoma tumors treated with anti-CTLA-4 therapy exhibit significant changes, including an elevated tumor mutation burden, increased inflammatory characteristics, and alterations in cell cycle processes, compared to untreated tumors." (PMID 40260303, 2025).
melanoma (continued). "In melanoma, immune checkpoint inhibitors such as PD-1 inhibitors and CTLA-4 inhibitors have become crucial treatment options." (PMID 41269529, 2025). "In this study, we comprehensively profiled 702 proteins in serum samples from stage III melanoma patients (n = 39) treated with neoadjuvant anti-PD-1 and anti-CTLA-4 therapy to identify circulating ICI biomarkers." (PMID 41291768, 2025). "Approved therapies, including immune checkpoint inhibitors (e.g., anti-PD-1 and anti-CTLA-4), have notably improved survival rates in melanoma." (PMID 39857682, 2025). "In this study, baseline plasma sCD27 was identified as a reliable biomarker discriminating response to anti-PD-1 versus anti-PD-1 + anti-CTLA-4 in two independent melanoma patient cohorts." (PMID 40148586, 2025). "Compared to anti-PD-1/PD-L1 inhibitors, monotherapy with anti-CTLA-4 inhibitors, such as ipilimumab, has only shown positive results in clinical trials for melanoma." (PMID 41236411, 2025). "In the CTLA-4 monotherapy group, RCTs about melanoma and prostate cancer using ipilimumab at 10 mg/kg of body weight were compared for their distribution within the same TRAE category." (PMID 39866435, 2025). "ICIs, such as anti-programmed death-1 (PD-1) and anti-cytotoxic T lymphocyte antigen-4 (CTLA-4) antibodies, are now standard treatments for advanced melanoma worldwide." (PMID 40647561, 2025). "In 2011, Ipilimumab, a monoclonal antibody (mAb) targeting cytotoxic T-lymphocyte-associated protein 4 (CTLA4), became the first ICI approved by the U.S. Food and Drug Administration (FDA) for treating advanced melanoma." (PMID 40276607, 2025). "For example, CTLA-4 inhibitors like ipilimumab can prompt a T-cell attack on the uveal melanocytes, leading to uveitis, especially in melanoma patients (melanoma antigens cross-react with ocular melanocytes in Vogt-Koyanagi-Harada syndrome–like fashion)." (PMID 41568391, 2025). "Another important revolutionary approach in melanoma is represented by immunotherapy, which sees drugs targeting immune checkpoints, such as anti-PD-1 and anti-CTLA-4 antibodies, demonstrating significant promise." (PMID 40277680, 2025). "Of note, the highest 5-year OS rate among therapies for advanced melanoma was observed with combined anti-CTLA-4 and anti-PD-1 checkpoint inhibition, which is most strongly associated with the highest incidence of immune-related adverse events." (PMID 41369373, 2025). "These included data from 69 melanoma patients receiving anti-PD1 or anti-PD1/CTLA4 therapy, 40 melanoma patients receiving anti-CTLA4, and the Cancer Genome Atlas cohort that predominantly includes patients not treated with ICB therapy." (PMID 41432764, 2025). "Blockade of Cytotoxic T-lymphocyte-associated protein 4 (CTLA-4) and Programmed Cell Death Protein 1 (PD-1) significantly improves progression-free survival of individuals with cancers, including melanoma." (PMID 40313772, 2025). "For this purpose, we analyzed a cohort of 64 malignant melanoma patients treated with anti-CTLA-4 therapy and for which tumor-normal whole-exome sequencing data and clinical data were available." (PMID 40872950, 2025). "Immune checkpoint inhibitors (ICI) have transformed cancer therapy, improving outcomes in malignancies like lung cancer, melanoma, and lymphoma by targeting PD-1, PD-L1, and CTLA-4 to enhance T cell-mediated tumor destruction." (PMID 40439712, 2025). "In B16 melanoma models subjected to radiotherapy and tumor antigen exposure, subsequent anti-CTLA-4 treatment markedly improved tumor clearance, whereas STING-deficient tumors exhibited reduced responsiveness and diminished CD8+ T cell infiltration." (PMID 41204180, 2025). "The increasing use of ICIs such as PD-1 and CTLA-4 inhibitors has significantly advanced melanoma treatment." (PMID 41375894, 2025). "In mouse models of melanoma, colorectal, breast, and ovarian tumors, the combined treatment of DNMTis and anti-CTLA-4 ICI can extend survival to some extent." (PMID 41132793, 2025).